SQOR (sulfide quinone oxidoreductase)
Description:
Catalyzes the oxidation of hydrogen sulfide with the help of a quinone, such as ubiquinone-10, giving rise to thiosulfate and ultimately to sulfane (molecular sulfur) atoms. Requires an additional electron acceptor; can use sulfite, sulfide or cyanide (in vitro). It is believed the in vivo electron acceptor is glutathione.
Synonyms: SQRDL; CGI-44; SQR; PRO1975
Tractability: Small molecule: a structure with a bound ligand is known; a high-quality ligand is known. PROTAC: ubiquitination databases record sites on it; a small molecule that binds it is known.
Target class: Enzyme; Oxidoreductase
Gene: Protein-coding gene on chromosome 15 (45,631,148 to 45,691,299, forward strand). Ensembl gene ENSG00000137767.
Subcellular location: Mitochondrion
Subcellular location (Human Protein Atlas): Mitochondria
Pathways (Reactome):
Metabolism: Sulfide oxidation to sulfate
Gene Ontology:
Molecular function: glutathione-dependent sulfide quinone oxidoreductase activity; protein binding; sulfide:quinone oxidoreductase activity; FAD binding; oxidoreductase activity
Biological process: sulfide oxidation
Cellular component: mitochondrion; mitochondrial inner membrane
Genetic constraint (gnomAD): Loss-of-function variants: 34 observed, 46.55 expected, observed/expected ratio (o/e) 0.73, 90% interval 0.56 to 0.97. The upper end of that interval is the gene's LOEUF score, 0.97, which puts it in group 4 of 6, group 1 being the genes least tolerant of losing a copy. Missense variants: 540 observed, 537.96 expected, observed/expected ratio (o/e) 1, 90% interval 0.94 to 1.08. Synonymous variants: 214 observed, 201.76 expected, observed/expected ratio (o/e) 1.06, 90% interval 0.95 to 1.19.
Gene-disease validity (ClinGen):
ClinGen rates the evidence that SQOR causes each of these diseases.
Leigh syndrome (autosomal recessive): Limited. A progressive neurological disease defined by specific neuropathological features associating brainstem and basal ganglia lesions.
Homologues: Orthologues: chimpanzee SQOR (99% identical), macaque SQOR (97% identical), dog SQOR (92% identical), pig SQOR (92% identical), rabbit SQOR (90% identical), rat Sqor (90% identical), mouse Sqor (87% identical), guinea pig SQOR (81% identical), tropical clawed frog sqor (73% identical), zebrafish sqor (71% identical), Drosophila melanogaster Sqor (49% identical), Caenorhabditis elegans Y9C9A.16 (41% identical), and 1 more.
Diseases named in the same sentence as SQOR in open-access papers:
SQOR is named in the same sentence as 58 diseases in open-access papers, as found by Europe PMC text mining. Sharing a sentence is not in itself a finding about the gene and the disease. The quoted sentences say what the papers report.
acute kidney injury (3 papers, 2020 to 2025). Sudden and sustained deterioration of the kidney function characterized by decreased glomerular filtration rate, increased serum creatinine or oliguria. "Although some studies have reported that SQOR was associated with neurological disorders and acute kidney injury (AKI) and where it alleviated AKI via influencing mitochondrial dysfunction, its exact function in the pathogenesis of colitis remains unclear." (PMID 40661137, 2025). "Animal studies demonstrated that long-term CoQ10 supplementation increases kidney CoQ10 levels sufficiently to rescue hydrogen sulfide (H2S) oxidation by increasing sulfide:quinone oxidoreductase (SQOR) levels and thereby preventing renal failure." (PMID 33114148, 2020).
colitis (3 papers, 2022 to 2025). Inflammation of the colon. "In summary, our study demonstrated that SQOR was downregulated during colitis and SQOR deficiency in the intestine aggravates DSS‐induced UC." (PMID 40661137, 2025). "Based on these, we found that SQOR deficiency promoted the increase of ROS levels in intestinal epithelial cells of colitis mice." (PMID 40661137, 2025). "It was found that SQOR deficiency drives severe DSS‐induced acute colitis." (PMID 40661137, 2025). "Notably, FITC‐dextran concentration in SqorCKO mice was higher than in SqorFL/FL colitis mice, indicating that SQOR deficiency increases intestinal permeability in DSS‐induced acute UC mice." (PMID 40661137, 2025). "Silencing SQOR leads to mitochondrial dysfunction and further aggravates the acute colitis induced by DSS in mice." (PMID 40661137, 2025). "Studies on the other enzymes, namely ETHE1, TST and SQOR, all show a lower expression in human and in animal colitis samples." (PMID 36421421, 2022). "Here, we observed that SQOR was downregulated during colitis." (PMID 40661137, 2025). "Thus, SQOR was further established as a regulator of colitis that functions in the intestinal epithelial cells." (PMID 40661137, 2025). "Therefore, SQOR regulates cytokines and chemokines expression involved in the ROS‐dependence inflammation in colonic epithelial cells, which are probably responsible for controlling colitis." (PMID 40661137, 2025). "After DSS stimulating, the colitis mice exhibited damaged and absent crypt abscesses, severe colonic tissue damage, and downregulated SQOR expression." (PMID 40661137, 2025).
colorectal cancer (3 papers, 2019 to 2025). A primary or metastatic malignant neoplasm that affects the colon or rectum. "This discovery offers new insight into treating conditions such as Leigh syndrome (caused by complex I deficiency) or colorectal cancers with CBS overexpression by indirectly modulating SQOR activity via metabolic supplementation (e.g., CoQ10)." (PMID 41210256, 2025). "We suggested for the first time that downregulation of mitochondrial genes, including ETHE1, SQOR, TST, and GPX3, would help colorectal cancer cells to produce more energy under hypoxic conditions through mechanisms that are different from “Warburg Effect”." (PMID 34249670, 2021).
ischemia (3 papers, 2021 to 2026). A hypoperfusion of the BLOOD through an organ or tissue caused by a PATHOLOGIC CONSTRICTION or obstruction of its BLOOD VESSELS, or an absence of BLOOD CIRCULATION. "This suggests that the repeated administration of AP39 before ischemia onset might similarly enhance the SQOR expression, which, in turn, might elevate the level of bound H2S and, thus, enhance the functions of mitochondria and rescue neurons in the ischemic area." (PMID 34360581, 2021).
Leigh disease (3 papers, 2022 to 2025). "In neurodegenerative diseases, SQOR dysfunction is linked to toxic H2S accumulation and neuroinflammation, and SQOR gene mutations can directly cause fatal Leigh syndrome." (PMID 41210256, 2025). "Here, we report that mice with a mutation in the gene encoding SQOR (SqorΔN/ΔN mice), which prevented SQOR from entering mitochondria, had clinical and pathological manifestations of Leigh syndrome." (PMID 38870029, 2024). "In contrast, in patients with Leigh syndrome caused by SQOR gene mutation, protein levels are markedly decreased in the mitochondria and cytoplasm of all cells." (PMID 38870029, 2024). "Pharmacological or dietary inhibition of H2S production prolonged survival in a preclinical model of Leigh syndrome caused by the SQOR gene mutation." (PMID 38870029, 2024). "Taken together, the results further support the pathogenetic role of H2S accumulation in Leigh-like disease in SqorΔN/ΔN mice and suggest a therapeutic strategy for patients with Leigh syndrome caused by SQOR gene mutations." (PMID 38870029, 2024). "Patients with Leigh syndrome caused by mutations in the gene encoding SQOR had T2-hyperintense bilateral, symmetrical lesions in the basal ganglia, thalamus, and hippocampus, as well as unilateral lesions in the cerebral cortex." (PMID 38870029, 2024). "In the recent report of 3 patients with Leigh syndrome caused by mutations in SQOR, the patients became symptomatic after gastrointestinal infections and prolonged fasting." (PMID 38870029, 2024). "The current study was designed to elucidate the pathogenetic mechanisms responsible for Leigh syndrome induced by mutations in the gene encoding SQOR and explore possible therapies." (PMID 38870029, 2024). "Our results suggest therapeutic strategies for the treatment of Leigh syndrome caused by mutations in the gene encoding SQOR." (PMID 38870029, 2024). "The Leigh syndrome associated with SQOR gene mutations has some similarities with ethylmalonic encephalopathy." (PMID 38870029, 2024). "In 2020, three patients with Leigh syndrome were found to have mutations in the gene encoding SQOR." (PMID 38870029, 2024). "In addition, we used this model to investigate two strategies to potentially treat patients with Leigh syndrome caused by pathogenic SQOR gene mutations." (PMID 38870029, 2024). "A potential limitation of this study is that the genetic mutation in SqorΔN/ΔN mice (homozygotes for 14-bp deletion of CCTGGTGATGGCCC at exon 2 of the SQOR gene) differed from that in Leigh syndrome patients (homozygotes for the pathogenic variant c.637G>A or c.446delT)." (PMID 38870029, 2024). "In conclusion, the current study revealed that mice in which SQOR is excluded from mitochondria recapitulate the clinical characteristics of patients with Leigh syndrome caused by SQOR gene mutations, including brain lesions, progressive motor dysfunction, and shortened lifespan." (PMID 38870029, 2024). "Sulfide:quinone oxidoreductase (SQOR) is an enzyme in the minor pathway of sulfate generation and its loss leads to excess hydrogen sulfide levels that cause encephalopathy and Leigh disease." (PMID 35495624, 2022). "Importantly, these observations suggest that pharmacological or dietary inhibition of H2S production by microbiota and host tissues may be a promising treatment for patients with Leigh syndrome caused by SQOR gene mutation." (PMID 38870029, 2024). "Here, we report that SqorΔN/ΔN mice, in which SQOR is excluded from mitochondria, recapitulate the clinical characteristics of Leigh syndrome, including progressive neurological deficits, brain lesions, and shortened lifespan." (PMID 38870029, 2024). "In 2020, mutations in the gene encoding sulfide:quinone oxidoreductase (SQOR), a mitochondrial protein, were identified as a cause of Leigh syndrome." (PMID 38870029, 2024).
Leigh disease (continued). "For Leigh syndrome due to SQOR genetic defects, reducing endogenous H2S production has proven beneficial: for example, oral metronidazole (to eliminate H2S-producing gut microbes) or a low-sulfur diet reversed neuro-metabolic abnormalities in SQOR-deficient mice." (PMID 41210256, 2025). "Because H2S inhibits mitochondrial complex IV activity, and the ability to catabolize H2S is likely to be impaired as a result of severely depressed SQOR protein levels, the authors hypothesized that increased levels of H2S may be contributing to the development of Leigh disease in these patients." (PMID 38870029, 2024).
osteoporosis (3 papers, 2015 to 2025). A condition of reduced bone mass, with decreased cortical thickness and a decrease in the number and size of the trabeculae of cancellous bone (but normal chemical composition), resulting in increased fracture incidence. "Conversely, SQOR dysfunction may be a driving factor in conditions like osteoporosis (bone density loss) and osteonecrosis (bone tissue death)." (PMID 41210256, 2025).
osteosarcoma (2 papers, 2024 to 2025). A usually aggressive malignant bone-forming mesenchymal neoplasm, predominantly affecting adolescents and young adults. "In contrast, in immunoresponsive tumors such as osteosarcoma, high SQOR expression enhances systemic antioxidant homeostasis and anti-tumor immune activity, thus inhibiting tumor progression (suppressing tumor growth)." (PMID 41210256, 2025). "Then, we performed in vivo experiments to further investigate the functions of SFXN4 and SQOR in osteosarcoma." (PMID 39569192, 2024). "The RT-qPCR, western blot and immunohistochemistry (IHC) analyses confirmed that SFXN4 displayed elevated expression at both RNA and protein levels in osteosarcoma tissues and cells, whereas SQOR exhibited heightened abundance in normal tissues and cells." (PMID 39569192, 2024). "In vivo and in vitro experiments demonstrated that the expression of SQOR could suppress the growth of osteosarcoma, whereas the expression of SFXN4 promoted it." (PMID 39569192, 2024). "Additionally, in vitro experiments also verified that SQOR inhibited the metastasis and invasiveness of osteosarcoma cells, while SFXN4 had the opposite effect." (PMID 39569192, 2024). "Notably, SFXN4 was found to be highly expressed in osteosarcoma tissues and cells; it promoted the growth, migration, and invasion of osteosarcoma cells, while SQOR had the opposite effect." (PMID 39569192, 2024). "Last but not the least, we conducted in vivo experiments to investigate the effects of SQOR and SFXN4 on the growth of osteosarcoma." (PMID 39569192, 2024). "However, further research is required to determine whether SQOR and SFXN4 influence the growth of osteosarcoma through the tumor microenvironment and tumor immunity." (PMID 39569192, 2024). "Multivariate Cox regression analysis confirmed that these 8 identified genes, including 2 protective elements (SQOR and PFKFB2) and 6 hazardous factors (MAFF, COL5A2, FAM162A, UQCRB, SFXN4, and COX6A2), could independently predict the overall survival of osteosarcoma samples." (PMID 39569192, 2024).
pancreatic cancer (2 papers, 2025). "In hypoxic tumors such as pancreatic cancer, high SQOR expression enhances resistance to ferroptosis, helping tumor cells tolerate oxidative stress (a pro-tumorigenic effect)." (PMID 41210256, 2025). "This implies that SQOR may promote the survival of pancreatic cancer cells in the harsh hypoxic microenvironment." (PMID 40375994, 2025).
renal fibrosis (2 papers, 2025). A final common manifestation of a wide variety of chronic kidney diseases characterized by glomerulosclerosis and tubulointerstitial fibrosis. "Mechanistically, deficiency of PC reduces sulfide:quinone oxidoreductase (SQOR) stability and accelerates mitochondrial damage, promoting mtDNA leakage and cGAS‐STING signaling activation, which in turn, leads to glycolysis increase and renal fibrosis." (PMID 39836535, 2025). "The loss of SQOR then induces mitochondrial damage and mtDNA release, activates the cGAS–STING innate immune pathway, and causes glycolytic reprogramming and excessive extracellular matrix deposition, thereby promoting renal fibrosis." (PMID 41210256, 2025). "Thus, we speculate that the PC pathway may regulate the activation of the cGAS‐STING signaling pathway, and the upregulation of glycolysis may be the downstream mechanism of PC/SQOR/STING‐mediated renal fibrosis." (PMID 39836535, 2025).
abscesses (1 paper, 2025). "Histological evaluation showed that SQOR deficiency led to an increased score of crypt abscesses, crypt loss, and ulceration, with a significant increase in immune cell infiltration in response to DSS stimulation." (PMID 40661137, 2025).
amyotrophic lateral sclerosis (1 paper, 2025). Amyotrophic lateral sclerosis (ALS) is a neurodegenerative disease characterized by progressive muscular paralysis reflecting degeneration of motor neurons in the primary motor cortex, corticospinal tracts, brainstem and spinal cord. "In a model of amyotrophic lateral sclerosis (ALS) caused by C9orf72 gene mutations, the pathogenic poly-dipeptide GA50 directly binds to and inhibits SQOR, leading to excessive NLRP3 inflammasome activation in microglia and consequent mitochondrial dysfunction." (PMID 41210256, 2025).
cerebral infarction (1 paper, 2025). An ischemic condition of the brain, producing a persistent focal neurological deficit in the area of distribution of the cerebral arteries. "For instance, neuron-specific overexpression of SQOR significantly reduced cerebral infarct size and delayed energy depletion in ischemic brain injury models." (PMID 41210256, 2025). "Neuron-specific SQOR overexpression has been shown to decrease the volume of cerebral infarction after stroke." (PMID 41210256, 2025).
Cerebral ischemia (1 paper, 2021). Restriction of arterial blood supply to the brain associated with insufficient oxygenation to support the metabolic requirements of the tissue. "In mice, global cerebral ischemia induced by 2VO decreased SQOR activity in the brain, leading to increased sulfide levels and the NADH/NAD+ ratio." (PMID 34035265, 2021). "Decreasing the cellular level of SQOR or preventing the mitochondrial localization of the enzyme makes the brains more sensitive to oxygen shortage, whereas neuron-specific expression of SQOR makes mice highly resistant to hypoxia and cerebral ischemia." (PMID 34035265, 2021). "Taken together, these results suggest that neuron-specific SQOR expression prevents sulfide accumulation and impairment of mitochondrial respiration in the brain, improves survival in severe hypoxia, and prevents ischemic brain injury and death after global cerebral ischemia." (PMID 34035265, 2021).
chronic heart failure (1 paper, 2025). "On the other hand, inhibiting SQOR in chronic heart failure (where H2S signaling is low) has been shown to be cardioprotective." (PMID 41210256, 2025). "In cardiovascular diseases, SQOR has dual functionality: in acute injuries such as myocardial ischemia–reperfusion, SQOR activation is protective, whereas in chronic heart failure, SQOR inhibition may be beneficial by increasing endogenous H2S levels." (PMID 41210256, 2025). "Under the metabolic rheostat framework, SQOR expression and activity are highly context-dependent: upregulation protects tissues from ischemia/reperfusion injury and ferroptosis, whereas inhibition may be beneficial in chronic heart failure or early cancer by allowing endogenous H2S to accumulate." (PMID 41210256, 2025).
chronic kidney disease (1 paper, 2023). Impairment of the renal function secondary to chronic kidney damage persisting for three or more months. "Interestingly, H2S oxidation impairment causes CoQ10 associated nephrotic syndrome, a chronic kidney disease related to CoQ10 deficiency, and it has been shown that reduced SQOR levels lead to increased ROS production, thus contributing to oxidative stress in conditions of CoQ deficiency." (PMID 36769128, 2023).
colorectal adenocarcinoma (1 paper, 2022). The most common type of colorectal carcinoma. "Here, we provide the first comparative analysis of the four human H2S-producing enzymes and the key H2S-catabolizing enzyme, sulfide:quinone oxidoreductase (SQOR), in Caco-2 human colorectal adenocarcinoma cells." (PMID 36290680, 2022).
Coma (1 paper, 2022). The complete absence of wakefulness and consciousness, which is evident through a lack of response to any form of external stimuli. "Individuals with SQOR mutations first present with coma in early childhood, suggesting a physiological role for SQOR in the brain beyond the 17-week gestational end point used to assess gene expression in the present study." (PMID 35495624, 2022).
diabetic kidney disease (1 paper, 2025). Progressive kidney disorder caused by vascular damage to the glomerular capillaries, in patients with diabetes mellitus. "In metabolic disorders such as diabetic nephropathy, changes in SQOR expression and activity are also closely tied to disease progression." (PMID 41210256, 2025). "On the other hand, in pathological conditions such as early diabetic nephropathy, inappropriate upregulation of SQOR leads to excessive consumption of signaling H2S, resulting in insufficient H2S signaling and exacerbated tissue damage." (PMID 41210256, 2025).
enteritis (1 paper, 2025). Inflammation of the small intestine. "Here, we generated SqorFL/FL‐Villin Cre mice, which lack SQOR specifically in intestinal epithelial cells, to investigate whether SQOR regulates of the occurrence and development of enteritis." (PMID 40661137, 2025).